SSPOP (SCO-spondin, pseudogene)
Description:
Involved in the modulation of neuronal aggregation (By similarity). May be involved in developmental events during the formation of the central nervous system (By similarity).
Synonyms: SSPO; SCO-spondin; KIAA0543; FLJ36112
Gene: Transcribed unitary pseudogene on chromosome 7 (149,776,042 to 149,833,829, forward strand). Ensembl gene ENSG00000197558.
Subcellular location: Secreted, extracellular space
Pathways (Reactome):
Disease: Defective B3GALTL causes PpS
Metabolism of proteins: O-glycosylation of TSR domain-containing proteins
Diseases named in the same sentence as SSPOP in open-access papers:
SSPOP is named in the same sentence as 14 diseases in open-access papers, as found by Europe PMC text mining. Sharing a sentence is not in itself a finding about the gene and the disease.
SSPOP shares sentences with these, for which no sentence is quoted: cancer (4 papers); Hydrocephalus (3); depression (2); tumor (2); epilepsy (1); idiopathic scoliosis (1); malignant brain tumors (1); melanoma (1); myopia (1); nodular melanoma (1); obstructive hydrocephalus (1); Parkinson disease (1); superficial spreading melanoma (1); thyroid cancer (1).